FOXD1 (forkhead box D1)
Diseases named in the same sentence as FOXD1 in open-access papers (continued):
Sharing a sentence is not in itself a finding about the gene and the disease.
osteosarcoma (5 papers, 2019 to 2022). A usually aggressive malignant bone-forming mesenchymal neoplasm, predominantly affecting adolescents and young adults. "Further work also suggests that miR-30a can target FOXD1 in human osteosarcoma cells so as to inhibit their proliferation." (PMID 32309442, 2020). "MiR-30a-5p inhibits migration of osteosarcoma cells through modulating FOXD1." (PMID 35313900, 2022).
clear cell renal cell carcinoma (4 papers, 2021 to 2024). "Clinical association studies suggest that FOXD1 is a determinant of patient outcome in clear cell renal cell carcinoma (ccRCC), and laboratory investigations have defined a role for this transcription factor in controlling the growth of tumors through regulation of the G2/M cell cycle transition." (PMID 36010951, 2022). "FOXD1 regulates the proliferation of clear cell renal cell carcinoma (ccRCC) cells, and ccRCC cells in which FOXD1 has been inactivated do not form tumors efficiently in an animal model." (PMID 36010951, 2022). "Due to the central role Foxd1 plays in regulating the embryonic development of the kidney, we are interested in understanding its role in clear cell renal cell carcinoma (ccRCC), which is the most common form of kidney cancer." (PMID 36010951, 2022). "Similarly, FOXD1 regulates histone modification to promote tumor growth in clear cell renal cell carcinoma." (PMID 37234983, 2023).
gastric cancer (4 papers, 2016 to 2025). A primary or metastatic malignant neoplasm involving the stomach. "Our results showed that FOXC1 and FOXD1 were upregulated in gastric cancer compared with normal tissues, which provides additional evidence for their roles of potential biomarkers." (PMID 27403158, 2016). "FOXD1 upregulation promotes gastric cancer cell proliferation, motility, and cisplatin resistance." (PMID 41214670, 2025).
ovarian carcinoma (4 papers, 2021 to 2024). A malignant neoplasm originating from the surface ovarian epithelium. "Conversely, FOXD1 is reported to suppress the proliferation of ovarian carcinoma cells and is correlated with chemoresistance of ovarian cancer patients." (PMID 36983712, 2023). "However, another study in ovarian cancer indicated that up-regulated FOXD1 could inhibit cell proliferation by inducing cell cycle arrest at G1 phase in ovarian cancer cells, and high FOXD1 expression was significantly correlated with favorable prognosis." (PMID 34269372, 2021).
colon cancer (3 papers, 2024 to 2026). "Forkhead box protein D1 (FOXD1) expression in colon cancer tissues is closely correlated with tumor size, differentiation grade, depth of invasion, lymph node metastasis, and TNM stage, and its high expression often predicts poor OS outcomes." (PMID 41614944, 2026). "Likewise, it has been demonstrated that inhibiting Forkhead box protein D1 (FOXD1), another well-known oncogene, decreases colon cancer cells’ capacity for invasion and migration." (PMID 40642075, 2025).
pancreatic ductal adenocarcinoma (3 papers, 2020 to 2022). An infiltrating adenocarcinoma that arises from the epithelial cells of the pancreas. "Overexpression of LncRNA OIP5-AS1 promotes the development of pancreatic ductal adenocarcinoma, and enhances the malignant phenotype by controlling miR-429/Forkhead Box D1 (FOXD1)/extracellular signal-regulated kinase (ERK) axis." (PMID 34281459, 2021).
squamous cell carcinoma (3 papers, 2021 to 2022). A carcinoma arising from squamous epithelial cells. "In line with published data on EMT, we assessed FOXD1 expression with known EMT inducers and repressors described in squamous cell carcinoma and cutaneous melanoma." (PMID 35954332, 2022). "However, unlike in squamous cell carcinoma and cutaneous melanoma, these EMT-like patterns are not clearly or significantly correlated with FOXD1 in UM." (PMID 35954332, 2022).
alopecia (2 papers, 2022 to 2024). Hair loss usually from the scalp. "The difference in the origin and, hence FoxD1 expression in the cranial and truncal dermal fibroblast–like cells, thus explains the distribution of the alopecia in the cKO animals and underlies the importance of HIF-P4H-2 in hair development." (PMID 35247391, 2022). "Phd2 deletion in FoxD1-lineage mesodermal cells (FoxD1-Cre) led to truncal alopecia by disturbing hair follicle development." (PMID 38509356, 2024).
cervical cancer (2 papers, 2021 to 2022). A primary or metastatic malignant neoplasm involving the cervix. "For cancers, miRNA-127-5p participants in cervical cancer progression through Forkhead box D1 (FOXD1) signaling." (PMID 33982667, 2021).
diabetes (2 papers, 2016 to 2023). "The identification of FOXD1 as a critical transcription factor for BCL-2 in the retina and kidney and the TRIM21-mediated regulation of FOXD1 stability complement our findings regarding therapeutic strategies for diabetes mellitus." (PMID 38092733, 2023). "Three of the four TF found for the SB gene-TF network (NF-κB, FOXA1, and FOXD1) have been reported to be involved in (human) kidney disease and diabetes." (PMID 26830357, 2016).
gastric adenocarcinoma (2 papers, 2016 to 2021). "At this point, forkhead box D1 (FOXD1), the cognate sense transcript of FOXD1‐AS1, attracted our attention because it has been verified to be upregulated in gastric adenocarcinoma tissues and is recognized as an oncogene in several cancers." (PMID 32460412, 2021).
head and neck carcinoma (2 papers, 2020 to 2023). A carcinoma that arises from the head and neck region. "Moreover, under the condition of overall survival probability, the Cox regression test using univariate and multivariate modes revealed that FOXD1 serves as an independent risk factor in comparison with other clinical parameters for predicting the prognosis of head and neck cancer patients." (PMID 32967107, 2020). "By using TCGA head and neck cancer database, we found that FOXD1 expression significantly (p = 0.036) correlates with a shorter time to new tumor event in patients receiving radiotherapy." (PMID 32967107, 2020). "We next evaluated the prognostic significance of FOXD1, FOXD2, FOXD3 and FOXD4 in TCGA head and neck cancer patients." (PMID 32967107, 2020). "Kaplan–Meier analysis revealed that FOXD1, as compared to FOXD2, FOXD3 and FOXD4, upregulation more significantly (p = 0.008) predicts a poor overall survival rate in TCGA head and neck cancer patients." (PMID 32967107, 2020). "Moreover, except FOXD3, we found that FOXD1, FOXD2 and FOXD4 are more significantly (p < 0.01) upregulated in primary tumor tissue compared to normal adjacent tissues derived from TCGA head and neck cancer patients." (PMID 32967107, 2020). "We further analyzed the transcriptional profile of FOXD1, FOXD2 and FOXD4 in the anatomic subdivision of TCGA head and neck cancer and found that the expression of FOXD2 in the hypopharynx and FOXD4 in the tonsil is relatively higher than other tissues, such as the oral cavity." (PMID 32967107, 2020).
kidney failure (2 papers, 2023 to 2024). An acute or chronic condition that is characterized by the inability of the kidneys to adequately filter the blood. "Taken together, these findings indicate that loss of Zeb2 in FOXD1+ stromal progenitors causes kidney fibrosis and kidney failure." (PMID 36445780, 2023). "Zeb2-deficient FOXD1+ stromal progenitors also took on a myofibroblast fate that led to kidney fibrosis and kidney failure." (PMID 36445780, 2023). "Loss of Zeb2 in FOXD1+ stromal progenitors leads to kidney failure and early mortality." (PMID 36445780, 2023). "Interestingly, we did not observe any glomerular cystic phenotype in stromal cell–specific Zeb2-cKO mice (Zeb2fl/fl;Foxd1-Cre+), suggesting a different underlying cause for kidney failure and early mortality in these mice." (PMID 36445780, 2023). "Of note, in contrast to Foxd2 mutant mice, homozygous Foxd1 KO mice die shortly after birth of kidney failure due to hypoplastic kidneys." (PMID 38154558, 2024). "In the absence of ZEB2, FOXD1+ stromal progenitors fail to differentiate into mature stromal cells such as pericytes and resident fibroblasts supporting normal kidney development and instead become myofibroblasts, leading to hypoplastic kidney, kidney fibrosis, and kidney failure." (PMID 36445780, 2023).
lipoma (2 papers, 2022 to 2024). A benign, usually painless, well-circumscribed lipomatous tumor composed of adipose tissue. "As a consequence, lipoma preferred partner (LPP) expression regarding FOXD1-induced EMT and chemoresistance in OSCC is upregulated." (PMID 38827805, 2024).
placental diseases (2 papers, 2019 to 2021). "Our results argue in favour of FOXD1 mutations’ central role in RPL, RIF, IUGR and PE pathogenesis via C3 and PlGF regulation and they describe, for the first time, a functional link between FOXD1 and implantation/placental diseases." (PMID 31395028, 2019).
preeclampsia (2 papers, 2019 to 2021). Preeclampsia is a hypertensive disorder of pregnancy that is characterized by new-onset hypertension with proteinuria presenting after 20 weeks of gestation, and depending on mild or severe forms may initially present with severe headache, visual disturbances, and hyperreflexia. "FOXD1 mutations have been implicated in obstetric complications including preeclampsia, IUGR, repeated implantation failure, and recurrent pregnancy loss through regulation of endometrial and placental genes." (PMID 34538263, 2021).
renal cell carcinoma (2 papers, 2021 to 2023). "To understand the function of FOXD1, we generated a loss of function renal cell carcinoma cell line using CRISPR/Cas9." (PMID 33761914, 2021). "Studies have shown that FOXD1 is upregulated and inversely related to patient survival in renal cell carcinoma." (PMID 37906341, 2023). "Foxd1 is essential for kidney development and mitochondrial metabolism, but its significance in renal cell carcinoma (ccRCC) has not been reported." (PMID 33761914, 2021).
serous ovarian carcinoma (2 papers, 2022 to 2024). "In highly differentiated serous ovarian cancer, the study discovered a mechanism that miR-30a-5p and miR-200a-5p targeted FOXD1." (PMID 38827805, 2024).
type 2 diabetes (2 papers, 2019 to 2024). "Based on our findings, the highly activated motifs of transcription factors FOXD1/2, PATZ1, and TLX2, were associated with the reported adverse effect, “Type II diabetes mellitus (Type II DM)”, a novel observation in this study." (PMID 31772269, 2019).
Autoimmunity (1 paper, 2022). The occurrence of an immune reaction against the organism's own cells or tissues. "FOXD1 is involved in autoimmunity through its regulation of IFNγ, IL2, IL4, and NFAT complexes." (PMID 35328504, 2022).
bladder cancer (1 paper, 2021).
breast tumor (1 paper, 2023). "It was found that Annexin A2 is highly expressed in breast tumor tissues and that FOXD1-dependent RalA-ANXA2-Src complex promotes circulating tumor cell formation in BC." (PMID 37189694, 2023).
coloboma (1 paper, 2017). An abnormality in which a part of a structure in one or both eyes is missing.
colorectal tumor (1 paper, 2021). "Developmental transcription factors like these are often found to be ectopically re-expressed in specific tumor cells, and this is the case for ZIC5 and FOXD1 in serrated colorectal tumor cells." (PMID 33423702, 2021).
floor of mouth tumor (1 paper, 2021). "The results revealed that high FOXD1 expression predicted worse OS especially in larynx tumor, hypopharynx tumor, and floor of mouth tumor." (PMID 34028536, 2021).
glaucoma (1 paper, 2022). Increased pressure in the eyeball due to obstruction of the outflow of aqueous humor. "Twelve of these genes, including PTPRB, HFM1, TAF1B, AAK1, FOXD1, EHMT1, and DNTT, are associated with glaucoma topical treatments (P < 1 × 10−5)." (PMID 36450729, 2022).
hyperglycaemia (1 paper, 2023). "Investigating the role of the FOXD1-BCL-2 axis in β-cell apoptosis associated with hyperglycaemia holds significant scientific interest." (PMID 38092733, 2023). "FOXD1, a transcription factor with known functions in renal and retinal development, is abundantly expressed in the retina, kidneys, central nervous system, and cardiomyocytes and is coincidentally associated with severe organ damage resulting from chronic hyperglycaemia." (PMID 38092733, 2023). "Herein, we unexpectedly found that FOXD1 plays a crucial role in regulating hyperglycaemia-induced apoptosis by directly modulating the transcription of BCL-2." (PMID 38092733, 2023). "In summary, we identified FOXD1 as a direct transcription factor for BCL-2 and identified a signalling axis (TRM21-FOXD1-BCL-2) underlying hyperglycaemia-induced cell apoptosis and tissue injury." (PMID 38092733, 2023). "Herein, we unexpectedly found that the E3 ligase TRIM21 interacted with and polyubiquitinated the transcription factor FOXD1 to control its protein stability under hyperglycaemic conditions, leading to hyperglycaemia-induced downregulation of FOXD1." (PMID 38092733, 2023). "Collectively, the results of the animal experiments validated the presence of hyperglycaemia-induced FOXD1-BCL-2 regulation and the beneficial effects of TBFs on hyperglycaemic injury through the regulation of this signalling axis." (PMID 38092733, 2023). "As a result, hyperglycaemia-induced degradation of FOXD1 shifts the balance to the proapoptotic state and initiates mitochondrial outer membrane permeabilization (MOMP)." (PMID 38092733, 2023). "Collectively, our findings provide evidence that FOXD1 is a new transcriptional regulator of BCL-2 under hyperglycaemic conditions and that an unrecognized TRIM21-FOXD1-BCL-2 axis transduces signalling related to hyperglycaemia-induced cell apoptosis and tissue injury." (PMID 38092733, 2023). "Furthermore, the finding that FOXD1 plays a vital role in hyperglycaemia-induced renal and retinal injury implies the therapeutic potential of targeting the FOXD1-BCL-2 axis to attenuate the progression of T2DM." (PMID 38092733, 2023). "Additionally, we found that TBFs, compounds extracted from the provincial food buckwheat, interfere with this cascade and effectively protect against hyperglycaemia-induced injury by preventing FOXD1 degradation." (PMID 38092733, 2023).
kidney tumor (1 paper, 2023). "Previous studies established connections between FOXD1 and kidney tumor development, as well as mitochondrial metabolism." (PMID 38390397, 2023).
lung fibrosis (1 paper, 2021). "Moreover, Foxd1 expressing progenitor cells play a role in lung development and lung fibrosis." (PMID 34538263, 2021).
lymph node metastasis (1 paper, 2024). "In HNSCC, overexpression of FOXD1 significantly associated with clinical stage and lymph node metastasis." (PMID 38827805, 2024). "Yet, no clear link was detected between FOXD1 high expression and sex (RR: 0.965; 95% CI: 0.835–1.116; p = 0.633), age (RR: 1.002; 95% CI: 0.880–1.142; p = 0.972) or lymph node metastasis (RR: 0.966; 95% CI: 0.662–1.410; p = 0.859)." (PMID 38827805, 2024). "Yet, none clear link was detected between FOXD1 overexpression as well as sex (RR: 0.965; 95% CI: 0.835–1.116; p = 0.633), age (RR: 1.002; 95% CI: 0.880–1.142; p = 0.972) or lymph node metastasis (RR: 0.966; 95% CI: 0.662–1.410; p = 0.859)." (PMID 38827805, 2024).
medulloblastoma (1 paper, 2019). A malignant, invasive embryonal neoplasm arising from the cerebellum. "For example, in medulloblastoma, FOXD1 acts as a tumor suppressor by targeting NKX2.2." (PMID 31795213, 2019).
Nephropathy (1 paper, 2023). A nonspecific term referring to disease or damage of the kidneys. "We also found that the FOXD1-BCL-2 axis is considerably involved in retinopathy and nephropathy in T2DM mice." (PMID 38092733, 2023).
polycythemia (1 paper, 2022). Abnormally high mass or concentration of red blood cells in the blood, either due to an increase in erythropoiesis or a decrease in plasma volume. "Polycythemia is also observed when HIF-P4H-2 is inactivated in the FoxD1 lineage (24 and this study), as the erythropoietin-producing kidney tubular interstitial fibroblasts are also derived from the FoxD1 lineage." (PMID 35247391, 2022).
thyroid carcinoma (1 paper, 2021). "FOXD1 expression was down-regulated in kidney renal clear cell carcinoma (KIRC), kidney renal papillary cell carcinoma (KIRP), thyroid carcinoma (THCA), and uterine corpus endometrial carcinoma (UCEC)." (PMID 34269372, 2021).
Werner syndrome (1 paper, 2019). "To further elucidate the relationship between the YAP–FOXD1 axis and human stem cell aging, we examined the expression levels of YAP, pan-TEAD, and FOXD1 in both replicative-senescent (RS) hMSCs and Werner syndrome (WS) hMSCs, a human stem cell model for premature aging disorder WS." (PMID 30933975, 2019).
Wilms tumor (1 paper, 2025). An embryonal neoplasm characterized by the presence of epithelial, mesenchymal, and blastema components. "GSEA analysis unveiled that genes upregulated in HEK293 cells expressing human ENLT1 and in ENL-mutant Wilms tumors were positively enriched in the sorted ENLT1 mutant FOXD1+ progenitor-derived cells." (PMID 40087269, 2025).